INS (insulin)
Diseases named in the same sentence as INS in open-access papers (continued):
Sharing a sentence is not in itself a finding about the gene and the disease.
Insulin resistance (continued). "Meanwhile, OXA-treated mice were significantly more responsive to insulin and the blood insulin level was significantly decreased, indicating that the treatment of OXA ameliorated insulin resistance in db/db mice." (PMID 26938239, 2016). "This indicates enhancement of insulin action in the liver and a protective effect of n-3 PUFA in the course of development of insulin resistance." (PMID 27258299, 2016). "Insulin resistance in 3T3-L1 adipocytes and C2C12 myotubes was induced by palmitate (16:0) treatment and confirmed by a decrease in AKT phosphorylation levels under insulin stimulation." (PMID 27527335, 2016). "A link between reduced insulin signaling in type 1 (insulinopenic) and type 2 (hyperinsulinemic) diabetic models was established with the recent demonstration of PNS insulin resistance." (PMID 28066166, 2016). "The effects of compounds 3a-3f and 4 and pioglitazone on insulin resistance were evaluated and compared using the DEX-induced insulin resistant model." (PMID 27853282, 2016). "Andres clamp technique is the most accurate method to diagnose IR, but its high cost limits the clinical acceptance; therefore, fasting insulin (FINS) and homeostasis model assessment of insulin resistance (HOMA-IR) are usually employed in clinic." (PMID 26770659, 2016). "Plasma glycine levels negatively correlated with the somatometric parameters (BW, BMI, and WC), VFA and SFA but correlated positively with insulin sensitivity (OGIS) and negatively with insulin resistance (HOMA-IR) and insulin secretion (HOMA-β and II)." (PMID 26788116, 2016). "The homeostasis model for insulin resistance (HOMA IR), as well as QUICKI (model for insulin sensitivity) was calculated for both treatments." (PMID 27872611, 2016). "TNF-α is believed to induce insulin resistance by a number of mechanisms such as increase in serine phosphorylation of IRS-1, which disrupts the insulin signaling cascade." (PMID 27379252, 2016). "In rodents, insulin downregulates hepatocyte Aqp9 gene transcription by acting on an insulin response element (IRE), which is consistent with AQP9 augmentations observed in animal models of insulin resistance." (PMID 27409609, 2016). "In mice fed regular chow, GYY4137 impaired insulin sensitivity as evidenced by the increase in plasma glucose and insulin concentrations as well as HOMA-IR index, the marker of insulin resistance." (PMID 28042862, 2016). "Vitamin D has been proposed to play an important role in the development of insulin resistance and the pathogenesis of T2DM by affecting either insulin sensitivity of beta-cell function." (PMID 26799569, 2016). "Therefore, inactivation of insulin/PPARγ pathway in epididymal fat tissue by aliskiren may reduce fat mass and adipocyte hypertrophy, thereby contributing to a decrease in body weight and insulin resistance." (PMID 26732252, 2016). "In this study, we demonstrated that acyl-ghrelin correlated negatively with TG, LDL-C, insulin, and HOMA-IR as components of metabolic syndrome and insulin resistance." (PMID 27348010, 2016). "Insulin resistance involves impaired activation of insulin substrate 1 (IRS1) and, subsequently, of the phosphatidylinositol 3-kinase (PI3K) pathway in insulin-sensitive tissues." (PMID 27437032, 2016). "Homeostatic model assessment of insulin resistance index (HOMA-IR) and β-cell function (HOMA-B), and the quantitative insulin sensitivity check index (QUICKI) were calculated." (PMID 27869717, 2016). "Acupuncture improves insulin resistance in OLETF rats, possibly via regulating expression of key insulin signaling related molecules." (PMID 27738449, 2016). "Insulin sensitivity indices GSI, ISI and DI decreased, and HOMA-IR increased with increasing insulin resistance among individuals." (PMID 27736893, 2016). "Up-regulated MAPK4 expression can lead to insulin resistance, and MAPK4 overexpression inhibits insulin-stimulated glucose uptake by negatively regulating the insulin signal-transduction pathway." (PMID 27846294, 2016).
Insulin resistance (continued). "In particular, a SIRT1 inhibitor EX527 significantly prevented BCH-induced increased phosphorylation of insulin signaling molecules, suggesting that SIRT1 activation was involved in BCH-induced improvement in insulin resistance in HF/HFr-fed mouse hepatocytes." (PMID 27874078, 2016). "Thus, PIK3R1 C-terminal mutations impair insulin signaling only in some cellular contexts and produce a subphenotype of insulin resistance resembling INSR dysfunction but unlike AKT2 dysfunction, implicating PI3K in the pathogenesis of key components of the metabolic syndrome." (PMID 27766312, 2016). "Although HDL cholesterol, homeostatic model assessment of insulin resistance (HOMA-IR) index, fasting glucose as well as fasting insulin levels were increased in B12R+ mice, the differences were not significant." (PMID 26835453, 2016). "SA treatment markedly decreased serum level of insulin and increased the value of QUICKI, which indicates that insulin resistance is improved by this agent (P < 0.05)." (PMID 26871288, 2016). "Taken together, our study suggests that in obesity, TNF-α induces vascular insulin resistance by increasing PTEN activity that negatively modulates Akt/eNOS/NO signaling and insulin vasodilation." (PMID 27562094, 2016). "Insulin resistance was induced only in mice subjected to an HFD, whereas control mice fed an LFD remained insulin sensitive, assessed by an insulin tolerance test (ITT)." (PMID 27047746, 2016). "To further confirm down-regulation of miR-194 in the insulin resistant state, we measured its expression in skeletal muscle from mice fed a HFD for 8 weeks, a well characterized mouse model of insulin resistance." (PMID 27163678, 2016). "In insulin tolerance tests, there was significant insulin resistance in both STAT males and females compared to controls, in the earliest time period after the insulin provocation." (PMID 27124954, 2016). "Certain microRNAs (miRNAs) targeting the molecules in the insulin signaling cascades are dysregulated by saturated fatty acids (SFA), which can lead to insulin resistance and type 2 diabetes." (PMID 27900351, 2016). "Fasting insulin resistance (HOMA-IR) was derived from C-peptide in Chinese and from insulin in Flemish using the Homeostasis Model of Assessment algorithm." (PMID 27073920, 2016). "Insulin resistance is often measured by using the homeostasis model assessment–insulin resistance (HOMA-IR) equation, which is a function of the product of fasting insulin and glucose levels." (PMID 27275336, 2016). "The data indicate that the mild insulin resistance observed in ND-fed knock-out mice cannot be explained by alterations in the phosphorylation/activation of IR and AKT in three major insulin-responsive tissues." (PMID 27456060, 2016). "Bivariate correlation analysis showed that FAIM expression was inversely correlated with BMI, plasma insulin levels and HOMA-IR, an established indicator of insulin resistance." (PMID 26866272, 2016). "Serum insulin levels and HOMA-IR were significantly increased at week 7 and 11 showing increasing insulin resistance and compensatory hyperinsulinemia." (PMID 27496100, 2016). "C2-ceramide, a short-chain ceramide analog, mimicked TNF-α to induce insulin resistance, decrease GLUT4 gene expression, and completely preclude insulin-stimulated glucose uptake and insulin-induced GLUT4 translocation to plasma membrane." (PMID 26903879, 2016). "Interestingly, type 2 diabetes is associated with a higher risk for hepatocellular carcinoma, which might be the consequence of a high prevalence of NAFLD in type 2 diabetes mellitus and insulin resistance with an increased hepatic triglyceride synthesis in insulin resistant subjects." (PMID 27649157, 2016). "Here, we examine the effect of acupuncture both on insulin resistance in OLETF rats and on the expression of insulin signaling components in rodent skeletal muscle." (PMID 27738449, 2016).
Insulin resistance (continued). "Little is known about the effects of exercise intensity on compensatory changes in glucose-stimulated insulin secretion (GSIS) when adjusted for adipose, liver and skeletal muscle insulin resistance (IR)." (PMID 27111219, 2016). "The expression level of membrane GLUT4 is used to evaluate the insulin responsiveness of GLUT4 from intracellular storage sites to the plasma membrane in skeletal muscle, which is faulty in insulin resistance." (PMID 27271603, 2016). "Levels of plasma insulin and HOMA-IR, a method used to quantify insulin resistance and β-cell function, were also significantly decreased by apigenin." (PMID 27213439, 2016). "In the present study, the plasma levels of six AAs exhibited relationships with the index of insulin resistance (HOMA-IR) and/or the index of insulin sensitivity (OGIS)." (PMID 26788116, 2016). "Owing to insulin resistance after TBI, most studies use exogenous insulin and dynamically monitor blood glucose to fight against hyperglycemia after TBI." (PMID 27626493, 2016). "Our results demonstrated that AnK display good antidiabetic activities; moreover, AnK treatment decreased blood insulin levels and finally improved HFD- induced insulin resistance." (PMID 27242912, 2016). "In the present study, an increase in serum insulin and HOMA-IR levels suggested there was insulin resistance in the HFD C7BL/6 mice." (PMID 27058520, 2016). "But in Japanese and Korean, impaired early-phase insulin secretion plays the more important role in isolated IGT and insulin resistance plays more important role in isolated IFG subjects." (PMID 26788515, 2016). "According to IR, the subjects were divided into an insulin resistance group (HOMA-IR >2.69) and insulin sensitivity group (HOMA-IR ≤2.69)." (PMID 27267043, 2016). "For this, we tested the association of HTGW with four T2D-related phenotypic traits (T2D, fasting blood glucose (FBG), fasting plasma insulin (FPI), and homeostatic model of assessment-insulin resistance (HOMA-IR))." (PMID 26798409, 2016). "In the present study, as association analysis indicated, patients with higher tryptophan level tended to present higher degree of insulin resistance (HOMA-IR and Matsuda index), and more active insulin secretion (1st- and 2nd- phase secretion)." (PMID 27598004, 2016). "We showed that at the peak of gestational insulin resistance in mice, gestational day 15 (G15), FFA2 is necessary to maintain glucose tolerance, glucose stimulated insulin secretion and β cell mass expansion." (PMID 27959892, 2016). "Homeostatic model assessment of insulin resistance (HOMA-IR) was computed, while transcriptional regulation of hepatic insulin signaling genes was also assessed." (PMID 26924713, 2016). "Therefore, although pathological levels of GCs have been well documented to be positively correlated with insulin resistance together with compensatory insulin secretion, suppression of ß-cell function may be a more fundamental pathophysiology of GCs on glucose metabolism than insulin resistance." (PMID 27861636, 2016). "Klotho inhibits signals of insulin/IGF-1 receptors (IR/IGF-Rs), and insulin receptor substrate 1 (IRS1), and induces insulin resistance." (PMID 27861640, 2016). "AESN markedly lowered serum insulin and blood glucose in HFD/ethanol-treated rats, suggesting that AESN markedly attenuated insulin resistance." (PMID 26927042, 2016). "Insulin increases endothelial nitric oxide (NO) production and endothelial NO synthase (eNOS) gene expression via PI3K and Akt, which is impaired in insulin resistance." (PMID 27247938, 2016).
Insulin resistance (continued). "In Ras and Src co-activated tumors, increased insulin signaling promotes SIK activity, revealing the SIK-Yki-Wg axis as the feed-forward circuit that reverses insulin resistance." (PMID 27604692, 2016). "Higher serum insulin and HOMA-2 insulin resistance was also observed among NWO compared with NWL (p = 0.004 and p = 0.003, respectively)." (PMID 27560824, 2016). "Studies in adipose tissue and cells have shown a role of hypoxia in insulin resistance and in the impairment of insulin action, while adipose tissue-specific disruption of HIF-1 in mice fed with high-fat diet improves insulin sensitivity." (PMID 27445976, 2016). "Compared with the normal TT group, body mass index (BMI), fasting insulin (FINS), and HOMA insulin resistance index (HOMA-IR) levels were significantly higher, but the luteinizing hormone (LH) levels were significantly lower in the low TT group (p < 0.05)." (PMID 27006953, 2016). "We find that acupuncture significantly improves insulin resistance in OLETF rats, possibly via regulating expression of key insulin signaling related molecules." (PMID 27738449, 2016). "The results from this study show that acupuncture improves insulin resistance in OLETF rats, possibly via regulating expression of key insulin signaling related molecules." (PMID 27738449, 2016). "Over the last two decades, accumulating evidence has suggested that certain miRNAs targeting the molecules in the insulin signaling cascade are expressed aberrantly in SFA-induced obesity, leading to insulin resistance and T2DM." (PMID 28036389, 2016). "Significant differences were found in serum insulin levels: +1.2 ± 1.2 versus +5.0 ± 1.1 μIU/ml (P = 0.02), and the conclusion was that the consumption of probiotic yoghurt maintains serum insulin levels and might help prevent developing insulin resistance during pregnancy." (PMID 27724923, 2016). "Phosphorylation at serine/threonine residues on IRS1 has been suggested to be a mechanism of insulin resistance by controlling IRS1 degradation and thus the ability of insulin to signal." (PMID 26956053, 2016). "In the present study, apigenin significantly decreased levels of fasting blood glucose, plasma insulin and HOMA-IR, a surrogate marker for insulin resistance, in HFD-fed mice." (PMID 27213439, 2016). "Homeostasis model assessment for insulin resistance (HOMA-IR) provides an estimate of IR derived from fasting glucose and insulin levels, with higher scores representing a greater degree of IR." (PMID 27517054, 2016). "The aim of this paper is to review the current evidence regarding the role of MYO-INS and DCI in the pathogenesis and treatment of diseases characterized by insulin resistance." (PMID 27688754, 2016). "On the other hand, Adipo-IR index, which is derived from measurements of fasting insulin concentration and of fasting free fatty acids (principally released by adipose tissue during fasting state), could be a method mainly reflecting adipose tissue insulin resistance." (PMID 28127113, 2016). "But the Mig-6d/d mice had increased fasting plasma glucose while the decreased concentration of fasting insulin and an improved HOMA-IR index still showed the improved insulin resistance (P < 0.01)." (PMID 28053990, 2016). "Higher fiber intake was observed to strongly associate (P < 0.001) with reduced baseline fasting plasma glucose (FPG), fasting plasma insulin (FPI), homeostasis model for assessment of insulin resistance (HOMA-IR), and glycated hemoglobin (HbA1C)." (PMID 27551309, 2016). "The HOMA‐IR index, a measurement of insulin resistance, was significantly lower in OVX + PPT mice than OVX + Veh mice, suggestive of improved insulin sensitivity with PPT." (PMID 27582063, 2016). "The rats fed with different dosages of guava juice in combination with or without trehalose for 4 weeks were evaluated the parameters including OGTT, plasma insulin, HbA1c, HOMA-IR (insulin resistance) and HOMA-β (β cell function and insulin secretion)." (PMID 26978332, 2016).
Insulin resistance (continued). "Using the HOMA2-IR cut-off value for insulin resistance of >1.8, as determined by the BRAMS study, our participants were substantially insulin resistant at baseline." (PMID 27187457, 2016). "Homeostasis model assessment was applied to assess the insulin resistance (HOMA-IR) and β-cell insulin secretion (HOMA-IS)." (PMID 28066696, 2016). "of the OGTT, significantly lower insulin secretion as measured with the HOMA-%B score, and comparable insulin resistance parameters." (PMID 27166795, 2016). "Because hypertriglyceremia interferes with glucose metabolism in muscle, which is the major organ of insulin action and glucose uptake, the TyG index seems to mainly reflect muscle insulin resistance whereas HOMA-IR mainly reflects hepatic insulin resistance." (PMID 27682598, 2016). "In conjunction with the sustained HFD-induced elevation of circulating insulin in cohort A mice, from 14 weeks onwards HFD-fed males from cohort A showed significant whole-body insulin resistance compared to their CD-fed littermates." (PMID 27055260, 2016). "Homeostasis model assessment of insulin resistance (HOMA-IR), quantitative insulin sensitivity check index and glucose insulin ratio were calculated to assess insulin resistance." (PMID 27087404, 2016). "In MNK1- or MNK2-KO mice, insulin-induced PKB phosphorylation was similar on the chow diet, but higher on the HFD than in WT/HFD animals, showing that insulin resistance is attenuated in MNK-KO/HFD mice." (PMID 27087055, 2016). "It illustrates the signaling of ceramide–ROS–insulin resistance in PA‐treated H4IIEC3 hepatocytes, and that NCDase‐Exos can inhibit this signaling cascade and rescue PA‐mediated H4IIEC3 insulin resistance." (PMID 27833848, 2016). "The insulin resistance subphenotype of SHORT syndrome patients, who have a functional defect lying between INSR and AKT2 in the insulin signaling pathway, closely resembles that seen in INSR dysfunction." (PMID 27766312, 2016). "IL-1β can negatively influence insulin signaling and subsequent glucose uptake, thereby demonstrating its role in HFD-induced insulin resistance." (PMID 27128935, 2016). "Insulin resistance was measured via the homeostatic model assessment of insulin resistance (HOMA-IR) and the quantitative insulin sensitivity check index (QUICKI)." (PMID 27763832, 2016). "Body mass index, waist circumference were measured, andfasting glucose and plasma insulin levels were determined, using the HOMA-IRindex to identify insulin resistance." (PMID 27007222, 2016). "The work we present here suggests that acupuncture improves insulin resistance in OLETF rats, possibly via regulating expression of key insulin signaling related molecules." (PMID 27738449, 2016). "Insulin resistance is prevalent in both the cases, but people with IFG have more hepatic insulin resistance and those with IGT have more skeletal muscle resistance with less effect on hepatic insulin sensitivity." (PMID 27894336, 2016). "In this study, hepatic global DNA methylation, and global acetylation of H3 and H4 histones in the HFD groups were in favor of increased insulin resistance, whereas the GBR and GABA groups produced changes that tended toward improved insulin sensitivity." (PMID 26842399, 2016). "Aliskiren increased insulin sensitivity and glucose transport activity in skeletal muscle of the HFD mice, contributing to amelioration of systemic insulin resistance." (PMID 26732252, 2016). "Along with obesity, HFD-fed mice displayed overt insulin resistance as indicated by the results from insulin tolerance tests, in which HFD-fed mice received twice the amount of insulin injection compared with LFD-fed mice." (PMID 27387960, 2016). "The insulin level in HFD control group was 28.97 ± 3.50 mU/L and the homeostasis model assessment of insulin resistance (HOMA-IR) level was 4.34 ± 0.41." (PMID 27058520, 2016).